CD44 (CD44 molecule (IN blood group))
Diseases named in the same sentence as CD44 in open-access papers (continued):
Sharing a sentence is not in itself a finding about the gene and the disease.
breast carcinoma (continued). "The CD44+/CD90+ phenotype, associated with tumorigenic breast cancer cells was present in 20.2±26.5% of selected cells." (PMID 28721373, 2016). "Western blotting showed that stem cell markers CD44 increased and CD24 decreased in the breast cancer cells with conditioned medium treatment, and the ratio of CD44+CD24− breast cancer cells became more than the control." (PMID 27325313, 2016). "Overall, our results demonstrate that the WNT5A-mediated reduction in CD44-AKT signaling plays an important role in inhibiting breast cancer cell migration and invasion." (PMID 27623766, 2016). "The outcome of this regulation is upregulated levels of miR-373 and reduced levels of CD44 in clinical breast carcinoma samples." (PMID 27671416, 2016). "In breast cancer cells this CD44 isoform switch led to reduced stability of the cytosine transporter xCT important for metastasis to the lung and to suppression of lung colonization." (PMID 27650542, 2016). "For example, the expression of CCL2 which is predominantely involved in breast cancer progression, was reduced in the CD44+/β1+ sub-population compared to Non- CD44+/β1+ cells (Data not shown)." (PMID 27835603, 2016). "The CD44+/CD24low/− phenotype is accepted by many researchers as a characteristic of the CSC sub-population in breast cancer." (PMID 27835603, 2016). "It has been reported that CD44 potentiates the adhesion of breast cancer cells to endothelial cells in the bone marrow, thus possibly mediating bone-specific metastasis." (PMID 27189371, 2016). "Recently, we reported that ZER abolishes CD44 expression through the inhibition of EGF/STAT-3 pathway in breast cancer cells." (PMID 26637807, 2016). "CD44 immunofluorescence staining revealed that both breast cancer cell lines (MDA-MB468-5A and MDA-MB231-5A) expressed reduced levels CD44 membrane protein compared to their counterpart controls, which were transfected with empty vector." (PMID 27623766, 2016). "Anti-CD44 DNA aptamer can form complexes with CD44 protein to inhibit the migration of the breast cancer cells." (PMID 27973403, 2016). "Recently, many studies have demonstrated a significant correlation between the level of CD44 expression and breast cancer tumorigenicity, which highlights the important role of CD44 in tumor progression and metastasis." (PMID 26974151, 2016). "All these in vitro studies for phenotypical and functional properties of CSCs were notably increased in the TS subpopulations for all cell lines, except for CD44+/CD24− expression in MDA-MB-231 breast cancer cells that is basally high in TP cells." (PMID 26752044, 2016). "CD44, a cell surface glycoprotein that regulates cell adhesion and migration and is connected to stem cell phenotype in different tumour types including breast cancer, was shown to be a direct ∆Np63 transcriptional target." (PMID 27724925, 2016). "In human breast cancer, the expression of CD44 and HA correlates with unfavorable clinical outcomes, highlighting their function in disease progression." (PMID 27009862, 2016). "To investigate the role of altered ERK1/2 signaling in the WNT5A-mediated inhibition of CD44, we treated breast cancer cell lines with U0126 (a selective inhibitor of MAP kinase)." (PMID 27623766, 2016). "Previous studies have identified CD44+ cells role in enhancing breast cancer cell migration and invasion." (PMID 26673618, 2016). "CD44, a breast cancer stem cell surface phenotype marker, was increased in MCF7_TG2 cells compared to control cells." (PMID 27609180, 2016). "In another study, PTX loaded and anti-CD44 antibodies functionalized PLGA-co-PEG polymeric micelles were prepared for treatment against breast cancer cell lines." (PMID 27679576, 2016). "Our previous studies in Dx-EVs showed a selective packaging of Ezrin, Radixin, Moesin and CD44 in resistant breast cancer cell-derived EVs." (PMID 26938523, 2016).
breast carcinoma (continued). "It was found that very small cell numbers of the CD44+/24–phenotype were capable of initiating mouse mammary tumors." (PMID 27229859, 2016). "CD44+/CD24− phenotypic cells were isolated from breast cancer tissues and breast carcinoma cell lines and were shown to exhibit self-renewal and high tumorigenic capacity." (PMID 26682001, 2016). "The importance of CD44 in supporting the dissemination of breast cancer cells to the bone was further investigated in vitro." (PMID 25888636, 2015). "It has been demonstrated that a small number of breast cancer cells with the CD44+/CD24- phenotype can form tumors after orthotopic injection into the mammary fat pad in immunocompromised mice." (PMID 26528725, 2015). "As shown by Huang at al., miR-373 promotes migration and invasion partly by targeting CD44 in breast cancer." (PMID 26196741, 2015). "As CD44+/CD24−/low is the classic stem cell marker in breast cancer, and approximately 99% of MDA-MB-231 cells are CD44+, we focused on the level of CD24 in MDA-MB-231 cells with or without NOP14 overexpression." (PMID 26213846, 2015). "Recent studies have shown the significant correlation between level of CD44 expression and breast cancer cell higher tumorigenicity and metastatic potential, thereby highlighting an important role of CD44 in tumor progression and metastasis." (PMID 26010608, 2015). "HA and CD44 co-localize in disseminated lesions within the lymph nodes, supporting a role for this receptor in mediating the HA-induced regional spread of breast cancer, consistent with recent immunohistochemical studies." (PMID 25888636, 2015). "Overexpression of CD44 in aggressive Ewing sarcoma and breast cancer cell lines, urged us to investigate functional relevance." (PMID 26189059, 2015). "We demonstrate that MDA-MB-231 breast cancer cells can be targeted and separated by anti-CD44-antibody-conjugated biotin-MBs." (PMID 25993512, 2015). "Breast cancer stem cells (CSCs), initially identified as CD44+/CD24- cells, are also known to express EMT markers." (PMID 26008969, 2015). "We first used the breast cancer as a model to analyze the correlation between IgGhigh cells and CD44+/CD24−/low BCSCs on adjoined sections by immunohistochemistry using RP215 and anti-human CD44v6, a CD44 isoform, which is more correlate to tumor invasion." (PMID 26472025, 2015). "Our study suggests that CD44 on cancer tissues and cancer cells is considerably more active compared with CD44 from normal control cells and that this activation plays a crucial role in selectively targeting therapy to breast cancer cells." (PMID 25909172, 2015). "Another potential mechanism is that CD44 functions in drug resistance as an antiapoptotic factor through up-regulation of Bcl-xL in breast cancer." (PMID 25823654, 2015). "Elevated CD44 expression, which occurs in tumor parenchyma and to a lesser extent in stromal cells, is associated with HER2-positive breast cancers and linked to reduced overall survival in this breast cancer subtype." (PMID 26106384, 2015). "In breast cancer, EpCAM+ CD44+ CD24− lineage− cells are 10 times more likely to form tumors than the EpCAM− CD44+ CD24− lineage− population." (PMID 25636521, 2015). "We and others have shown that Fra-1 promotes metastasis through various molecules: ADORA2B in breast cancer, MMPs in breast cancer and in lung epithelial cells, CD44 in mesothelioma, AXL in bladder cancer, FAK and EZH2 in colon cancer." (PMID 26646695, 2015). "Only CSC-like cells (i.e. CD44+/CD24-) in breast cancer cells respond to TGF-β1 induction for increasing in GSN expression such as to maintain their invasive phenotype." (PMID 26482896, 2015). "Our previous and current works pivotally connect two critical regulatory axes, GATA3/miR29b and miR29b/AF1q/TCF7/CD44/KISS1, associated with the Wnt pathway for breast cancer metastasis." (PMID 26079538, 2015).
breast carcinoma (continued). "CD34+ was used for leukemia-initiating cells, and CD44+CD24− or ALDH1+ was used to enrich breast cancer-initiating cells." (PMID 26376676, 2015). "The capacity to increase cell-cell and cell-matrix adhesion is consistent with our observations that CD44 increases the efficiency of distant metastasis of basal-like breast cancer in vivo." (PMID 26447611, 2015). "In conclusion, our data demonstrate that TGF-β1 induces EMT by the transactivation of EGF signaling through HA/CD44 in lung and breast cancer cells." (PMID 26005723, 2015). "This experimental observation reaffirms our correlation of CD44-positivity in primary breast cancer tissue with reduced disease-free survival in patients with confirmed distant metastasis." (PMID 25888636, 2015). "In contrast, luminal breast cancer tumors mostly consist of CD44–/CD24+ cells and are thought be more differentiated." (PMID 25993512, 2015). "CD44 is a cell-surface glycoprotein receptor for hyaluronan (HA) and is an accepted marker for isolating tumourigenic, stem-like breast cancer cells." (PMID 26447611, 2015). "HA binding of CD44 on normal cells was observed when normal cells were co-cultured with breast cancer cells, indicating that the conversion of CD44 from an inactive state to an active state." (PMID 25909172, 2015). "The percentage of CD44+CD24− cells within breast cancer cell lines was found to be uncorrelated with tumorigenicity." (PMID 25905435, 2015). "In conclusion, our study indicates that in combination, EGFR and CD44/CD24 expression status are powerful identifiers of breast cancer patient subgroups with different clinical behavior." (PMID 25429827, 2015). "Only several years later it was observed that CD44+CD24−/low cells isolated from human breast cancer can induce breast cancer in NOD/SCID mice, while the remainder of cells failed to induce tumors." (PMID 26593898, 2015). "Cancer stem cells with a CD44+/CD24−/low phenotype were isolated from two other breast cancer cell lines (MCF-7 and T47D)." (PMID 26694341, 2015). "Here we found low levels of miR-34a and high levels of SIRT1 in CD44+/CD24− breast cancer stem cells (BCSCs)." (PMID 25826085, 2015). "BCSCs expressing CD44+CD24−/low surface markers isolated from human breast cancer clinical specimens were found to be highly tumorigenic." (PMID 26305906, 2015). "Previous studies have shown that reducing the expression level of CD44 by siRNA increased sensitivity to doxorubicin in breast cancer." (PMID 25823654, 2015). "Breast cancer was one of the first solid malignancies in which CSCs were identified and characterized, mostly immunophenotypically as lin-/CD44+/CD24- cells." (PMID 25774169, 2015). "CD44 expression correlates with specific subtypes of breast cancer, including triple negative and endocrine resistant breast cancers." (PMID 26106384, 2015). "The standard form of CD44 (CD44s) and CD44v6 are involved in breast cancer cell adhesion and motility via interactions with HA." (PMID 26029216, 2015). "CD24 expression was a poor prognostic marker in HR-positive breast cancer, and CD44 expression was a good prognostic marker in the HR-negative group." (PMID 25429827, 2015). "CD44 was first described as a CSC marker in breast cancer and HNSCC, and it has since been used as a CSC marker and prognostic factor for SCC." (PMID 26626427, 2015). "Breast cancer stem cells (BCSCs) first isolated by surface marker CD44+/CD24−/low possess the characteristic of unlimited self-renewal and are able to generate differentiated descendants." (PMID 25686831, 2015). "The results indicate that targeted biotin-MBs conjugated with anti-CD44 antibodies can be used to separate MDA-MB-231 breast cancer cells; more than 90% of the cells were collected in the MB layer when the ratio of the MBs to cells was higher than 70:1." (PMID 25993512, 2015).
breast carcinoma (continued). "Treatment with doxorubicin, which is widely used in the adjuvant or metastatic settings in breast cancer, similarly induced CD44 expression with reduced cleaved caspase-3 levels." (PMID 25669750, 2015). "CD44/CD24 expression profiles showed a large variability within breast cancer subtypes especially for TNBCs." (PMID 26504780, 2015). "The clinical significance of CD44 was evaluated by immunohistochemical analysis of a breast cancer tissue microarray constructed using primary tissue from 448 patients." (PMID 25888636, 2015). "CD44+/CD24− cells are considered to be the cancer stem-like cells in breast cancer, and we use this group as an indicator of the proportion of cancer stem-like cells in our cell populations." (PMID 26016502, 2015). "In this study, we have discovered that RP215-recognized IgG was overexpressed CSC-like cells such as CD44+/CD24−/low of breast cancer cells, and the p63+ adult stem/progenitor cells of many stratified epithelium." (PMID 26472025, 2015). "In breast cancer cells, cell-surface Hyal2 has been shown to form a functional complex with CD44 and NHE1." (PMID 25716319, 2015). "In breast cancer, the expression of stem cell markers such as CD44, ATP-binding cassette sub-family G member 2 (ABCG2) and aldehyde dehydrogenase A1 (ALDHA1) can be used to selectively isolate a cell population enriched in CSC." (PMID 26517518, 2015). "Breast cancer cells that have low expression of CD24 in combination with high expression of CD44 (CD24−/CD44+) and high aldehyde dehydrogenase (ALDH) activity are known as breast cancer stem cells (BCSCs)." (PMID 26301220, 2015). "CD44 expression is elevated in basal-like breast cancer (BLBC) tissue, and correlates with increased efficiency of distant metastasis in patients and experimental models." (PMID 26447611, 2015). "Intriguingly, among human breast cancer cell lines, the CD44+ cells with a high level of ALDH activity show increased tumor formation and lung colonization abilities compared to ALDHlow/CD44low cells, indicating a role of CD44 in the cancer metastatic process." (PMID 26064420, 2015). "Two histological studies examining breast cancer patient tumor samples prior to and after primary systemic chemotherapy evidenced an increase in therapy-resistant CD44+/CD24−/low cells after treatment." (PMID 26448751, 2015). "Breast cancer stem cells (BCSCs) with cell surface phenotype of CD44+/CD24−/low/Lineage−low were first identified and isolated by Al-Hajjet al. in 2003." (PMID 25826085, 2015). "We analyzed 34 clinical primary tumor and normal breast tissues and demonstrated that CD44 was in an active state on breast cancer cells but in an inactive state on normal cells." (PMID 25909172, 2015). "As breast cancer progenitor cells have been previously identified as CD44+CD24−/low cells, the cellular expression of CD44 and CD24 was evaluated by flow cytometry." (PMID 25405855, 2015). "Here, we report the isolation of subsets of EpCAM-negative breast cancer CTCs containing stem-cell properties (CD44+/CD24−) by multiparametric flow cytometry with a combinatorial uPAR and int β1 expression and their abilities to grow long-term in vitro." (PMID 26631983, 2015). "SAHA treatment significantly downregulated the expression of CAIX (p < 0.05, n = 3) and the expression of the breast cancer stem cell marker CD44 (p < 0.05, n = 3)." (PMID 26305601, 2015). "Several stemness markers have been described for the various histological subtypes of breast cancer, such as CD44, CD24, CD133, ALDH1, and ABCG2." (PMID 26504780, 2015). "Our group has shown that P-cadherin is directly associated with the expression of the breast stem cell markers CD44, CD49f and the activity of aldehyde dehydrogenase in human breast carcinomas and in a series of breast cancer cell lines." (PMID 26438065, 2015).
breast carcinoma (continued). "Accordingly, an IL-6/STAT3 pathway was preferentially active in CD44+/CD24- breast cancer stem cells and PTEN was shown to negatively regulate TIC manteinance through STAT3-dependent signalling." (PMID 26486080, 2015). "In summary, we demonstrate the capacity of HA-induced CD44-mediated signaling to increase the efficiency of integrin-mediated adhesion of metastatic breast cancer cells to vascular endothelium and Fibronectin-enriched matrices." (PMID 26447611, 2015). "In CD44+/CD24− stem-like cells compared to other cell populations from breast cancer cell lines and breast tumors, the expression of ATM was significantly increased." (PMID 26273424, 2015). "Earlier studies have shown that breast cancer cells contain stem-cell like cells exhibiting CD44+CD24-/low marker expression and these cells possess more than 50 fold increased tumorigenic capacity when compared to the other cells of tumour mass." (PMID 26355461, 2015). "Although a number of HA receptors have been identified, the two that have been best characterized and are to date most relevant to inflammation and breast cancer are CD44 and RHAMM." (PMID 26106384, 2015). "CD44 has already been targeted in breast cancer therapy using monoclonal antibodies and HA-tagged drugs." (PMID 25909162, 2015). "Breast cancer CSCs have been identified by cell-surface marker combinations, most commonly CD44+CD24lo/−, as well as by expression of ALDH1, so we investigated the status of these CSC markers in our SORE6+ population." (PMID 25497455, 2015). "For example, in MCF7 cells, members of the miR-520/373 family, which potently suppressed phospho-Akt levels associated with the inhibition of cell proliferation, were reported to promote breast cancer metastasis by targeting CD44." (PMID 25630670, 2015). "It is believed that CD44+/CD24− breast cancer cells are highly invasive and radioresistant and chemoresistant." (PMID 25429827, 2015). "The breast cancer spheroids generated by us under specific culture conditions showed altered levels of the breast CSC markers CD44+CD24-/low." (PMID 26355461, 2015). "Basal-like breast cancer tumors are known to be abundant in CD44+/CD24– cells and exhibit stem-cell-like characteristics." (PMID 25993512, 2015). "In the basal-likeMDA-MB-231 breast cancer cell model, the subpopulation of CD44 (+) CD24 (low+) cells exhibits stem cell properties in vitro and in vivo, metastatic gene signatures and greater invasion and metastatic potential." (PMID 26121683, 2015). "CD44 expression, aldehyde dehydrogenase activity, and mammosphere-formation assays were used to monitor stem cell-like characteristics of breast cancer cells." (PMID 26312209, 2015). "In conclusion, our study confirms that the expression of CD44 increases the efficiency with which tumourigenic breast cancer cells can successfully complete the distant steps of the metastatic cascade." (PMID 25888636, 2015). "Balaji Krishnamachary etc. showed HIF-1α was a regulator of CD44 expression in breast cancer cells under hypoxic conditions." (PMID 26323509, 2015). "CD133 has been used as a putative stem cell marker in glioblastoma and colon cancer; CD34 expressing tumour epithelial cells have been used as a marker in cutaneous cancer; and CD44 expressing cells have been used as a marker in breast cancer." (PMID 25881239, 2015). "Breast cancer stem cells (BCSCs) with biomarker of ESA+CD44+CD24-/low have been reported as the origin of different pathological types of breast cancer and the radical cause of drug resistance, tumor relapse and metastasis in breast cancer." (PMID 26400441, 2015). "For example, human breast cancer cells implanted in epirubicin-treated mice were found to be considerably enriched with CD44+/CD24−/low cells." (PMID 26305906, 2015).